FMNL1 (formin like 1)
Description:
Plays a role in actin cytoskeleton dynamics and regulation of cell shape.
Synonyms: C17orf1; C17orf1B; FMNL; FHOD4; KW-13
Tractability: Small molecule: a structure with a bound ligand is known. Antibody: UniProt places it where antibodies can reach, with high confidence; its Gene Ontology location is reachable by antibodies, with medium confidence. PROTAC: ubiquitination databases record sites on it; its protein half-life has been measured.
Gene: Protein-coding gene on chromosome 17 (45,220,736 to 45,247,319, forward strand). Ensembl gene ENSG00000184922.
Subcellular location: Cytoplasm; Cell membrane; Cytoplasmic vesicle, phagosome; Cytoplasm, cell cortex (Isoform 3); Cell projection, bleb
Subcellular location (Human Protein Atlas): Cytosol
Pathways (Reactome):
Signal Transduction: CDC42 GTPase cycle; RAC1 GTPase cycle; RHO GTPases Activate Formins
Gene Ontology:
Molecular function: GTPase activating protein binding; protein binding; actin filament binding; small GTPase binding; actin binding; profilin binding
Biological process: actin filament severing; cell migration; cortical actin cytoskeleton organization; regulation of cell shape; actin cytoskeleton organization; cytoskeleton organization; regulation of cell morphogenesis
Cellular component: extracellular exosome; membrane; cytosol; phagocytic vesicle; plasma membrane; bleb; cell cortex; cytoplasm
Genetic constraint (gnomAD): Loss-of-function variants: 43 observed, 114.85 expected, observed/expected ratio (o/e) 0.37, 90% interval 0.29 to 0.48. The upper end of that interval is the gene's LOEUF score, 0.48, which puts it in group 2 of 6, group 1 being the genes least tolerant of losing a copy. Missense variants: 1,191 observed, 1,397.7 expected, observed/expected ratio (o/e) 0.85, 90% interval 0.81 to 0.89. Synonymous variants: 613 observed, 564.24 expected, observed/expected ratio (o/e) 1.09, 90% interval 1.02 to 1.16.
Homologues: Orthologues: chimpanzee FMNL1 (99% identical), macaque FMNL1 (98% identical), dog FMNL1 (93% identical), pig FMNL1 (91% identical), rat Fmnl1 (91% identical), mouse Fmnl1 (88% identical), guinea pig FMNL1 (76% identical), zebrafish fmnl1a (58% identical), tropical clawed frog fmnl1 (57% identical), Drosophila melanogaster Frl (42% identical), Caenorhabditis elegans frl-1 (34% identical), Caenorhabditis elegans daam-1 (20% identical), and 2 more. Paralogues in human: FMNL2 (58% identical), FMNL3 (54% identical), DAAM1 (23% identical), DAAM2 (23% identical), DIAPH3 (21% identical), DIAPH1 (21% identical), DIAPH2 (19% identical), INF2 (19% identical), FHOD3 (19% identical), FMN2 (17% identical), FHOD1 (16% identical), GRID2IP (15% identical), and 6 more.
Diseases named in the same sentence as FMNL1 in open-access papers:
FMNL1 is named in the same sentence as 44 diseases in open-access papers, as found by Europe PMC text mining. Sharing a sentence is not in itself a finding about the gene and the disease. The quoted sentences say what the papers report.
glioblastoma (7 papers, 2019 to 2025). The most malignant astrocytic tumor (WHO grade IV). "Previous studies have linked high FMNL1 expression to a poor prognosis in a variety of cancers, including clear cell renal cell carcinoma, gastric cancer, and glioblastoma." (PMID 36124068, 2022). "For instance, FMNL1 KD in glioblastoma cell lines downregulates DIAPH1 protein levels, whereas FMNL1 overexpression upregulates them, enabling malignant cells to migrate slower of faster, respectively, than control cells." (PMID 34685534, 2021). "Our data were consistent with previous studies reporting FMNL1 was overexpressed in glioblastoma, lung cancer and nasopharyngeal carcinoma, and was associated with patient prognosis." (PMID 33324547, 2020). "VERHAAK and PHILLIPS glioblastoma mesenchymal genes and VERHAAK and PHILLIPS glioblastoma proneural genes were significantly associated with high and low FMNL1 expression, respectively." (PMID 31861134, 2019). "FMNL1 was an independent predictor of poor prognosis in a cohort of 217 glioblastoma multiforme cases (p < 0.001)." (PMID 31861134, 2019). "Conversely, FMNL1 downregulation suppressed glioblastoma multiforme cell migration and invasion via DIAPH1 and GOLGA2, respectively." (PMID 31861134, 2019). "We studied FMNL1 expression in glioblastoma samples using immunohistochemistry." (PMID 31861134, 2019). "FMNL1 was upregulated in various malignancies, like lymphoma, T non-Hodgkin's lymphomas, GBM (Glioblastoma multiforme), NSCLC and NPC 19,20,21." (PMID 34659547, 2021).
leukemia (7 papers, 2018 to 2024). A malignant (clonal) hematologic disorder, involving hematopoietic stem cells and characterized by the presence of primitive or atypical myeloid or lymphoid cells in the bone marrow and the blood. "High FMNL1 expression has been shown to be associated with more aggressive leukemia by promoting infiltration and has also been shown to be associated with metastasis in certain solid tumors." (PMID 39430739, 2024). "Furthermore, the Formin FMNL1 is overexpressed in lymphoid malignancies and recently FMNL1 has been implicated in regulating leukemia proliferation and migration." (PMID 30294591, 2018). "Recently, additional leukemia-specific TCRs have been discovered, which bind to Formin-like protein 1 (FMNL1) and are restricted to MHC class I/II." (PMID 39411712, 2024). "This is particularly relevant as exosome secretion is required for directionally persistent and efficient in vivo movement of cancer cells, and it is known that FMNL1 stimulates both leukemia cell proliferation and migration." (PMID 39479958, 2024). "FMNL1 increases the proliferation of leukemia cells, and FMNL3 promotes cell proliferation and clonogenicity in colorectal cancer." (PMID 34193109, 2021). "In addition, FMNL1 promotes proliferation and migration of leukemia cells and mediates posterior perinuclear actin polymerization to promote T lymphocyte effector cell migration to inflammatory sites to enable T cell-mediated autoimmunity." (PMID 39479958, 2024). "FMNL1 is a formin-related protein highly expressed in hematopoietic cells and also overexpressed in leukemias, its interaction with AHNAK induced the localization of the latter at the cell membrane thereby suggesting a potential role of both of these actors in pathogenesis." (PMID 38918490, 2024). "Based on the role of mDia1 in cytoskeletal rearrangements and lymphocyte motility, as well as the reported role of FMNL1 in leukemia migration, we sought to determine the possible role of mDia1 in leukemia cell migration, dissemination, and progression in vivo." (PMID 30294591, 2018). "Increasing numbers of leukemia-specific TCRs have been recently identified, including MHC class I/II-restricted TCRs with specificity for Formin-like protein 1 (FMNL1) with potent activity against CLL cells." (PMID 30622438, 2019).
clear cell renal cell carcinoma (6 papers, 2020 to 2025). "As a result of the immunohistochemistry and mRNA expression study performed in 306 clear cell renal cell carcinoma tissues, it was observed that FMNL1 was highly expressed in clear cell renal cell carcinoma and increased prometastatic activity." (PMID 40864802, 2025). "FMNL1 is primarily expressed in immune cells and tissues such as clear cell renal cell carcinoma and the nasopharyngeal carcinoma, despite its role as a critical oncogene in a variety of cancers." (PMID 36124068, 2022). "Some examples of strong correlations are DAAM1 in breast cancer; FMNL1 in nasopharyngeal cancer, non-small cell lung cancer, and clear cell renal cell cancer; and of FMNL3 in colorectal cancer." (PMID 34685534, 2021). "Yet the clinical significance and biological function of FMNL1 in clear cell renal cell carcinoma (ccRCC) remain unclear." (PMID 33324547, 2020).
nasopharyngeal carcinoma (6 papers, 2020 to 2023). A carcinoma arising from the nasopharyngeal epithelium. "The role of formin-like protein (FMNL1) was examined in human nasopharyngeal carcinoma (NPC) pathogenesis." (PMID 34290983, 2021). "Examples of this function are DIAPH1-3 and DAAM1 in breast cancer, DIAPH1 in glioma, FMNL1 in nasopharyngeal carcinoma, FMNL2 in colorectal cancer, and FHOD1 in oral squamous carcinoma." (PMID 34685534, 2021). "Previous studies demonstrated that FMNL1 was responsible for the tumor progression in nasopharyngeal carcinoma and non-small cell lung cancer." (PMID 33324547, 2020). "Strikingly, FMNL1 was also found to be upregulated in solid tumors, such as nasopharyngeal carcinoma, non-small cell lung cancer, and gioblastoma." (PMID 33324547, 2020). "To date, investigations on the role of FMNL1 in solid cancers, such as ccRCC, lung cancer and nasopharyngeal carcinoma, indicate FMNL1 as a promising prognostic marker to predict the outcomes of cancer patients." (PMID 33324547, 2020). "FMNL1 increased cell aggressiveness in nasopharyngeal cancer by epigenetically upregulating MTA1." (PMID 36124068, 2022). "In the study of nasopharyngeal carcinoma, in vivo and in vitro results also illustrated that overexpression of FMNL1 promoted cell migration, invasion, invadopodia formation, and enhanced aggressiveness ability of NPC cells." (PMID 34659547, 2021).
gastric cancer (4 papers, 2021 to 2023). A primary or metastatic malignant neoplasm involving the stomach. "In our previous study, we uncovered that Formin-like gene 1 (FMNL1) was tightly related to immune infiltration in gastric cancer." (PMID 37859818, 2023). "We further characterized FHOD1 and FMNL1 protein expression levels and patterns in gastric cancer cells." (PMID 34115237, 2021). "To characterize FHOD1 and FMNL1 expression in gastric cancer cell lines and validate antibodies for tissue stainings, we studied FHOD1 and FMNL1 protein expression in three publicly available cell lines; MKN28, AGS and MKN45." (PMID 34115237, 2021). "To assess the prognostic significance of FHOD1 and FMNL1 expression in intestinal gastric cancer, we used the KM-plotter database for Kaplan–Meier survival analyses." (PMID 34115237, 2021). "In addition, we characterized FHOD1 and FMNL1 expression in cultured gastric cancer cells." (PMID 34115237, 2021). "Our study is the first one to characterize these formins in intestinal gastric cancer tissue samples and investigate the correlation between cancer cell-specific FHOD1 and FMNL1 protein expression and intratumoral T lymphocyte infiltration." (PMID 34115237, 2021). "To study the localization and expression pattern of these formins in gastric cancer cells, we performed double immunofluorescence staining of F-actin and FHOD1 or FMNL1 in MKN28, AGS and MKN45 cells (respectively)." (PMID 34115237, 2021). "As an example of self-criticism, we revealed that FMNL1 was tightly related to immune infiltration in gastric cancer in our previous research 4, but no in-depth analysis was performed." (PMID 37859818, 2023).
lymphoma (3 papers, 2021 to 2022). A malignant (clonal) proliferation of B- lymphocytes or T- lymphocytes which involves the lymph nodes, bone marrow and/or extranodal sites. "Additionally, FMNL1 is expressed in a variety of malignant tissues, while an antigenic peptide (FMNL1-PP2) derived from FMNL1 was experimentally shown to induce specific T cells to exert killing effects on tumors, including lymphomas." (PMID 35371070, 2022). "The overexpression of FMNL1 in blood-derived tumor cells has led to the development of novel approaches to cancer treatment, such as the use of cytotoxic T cell clones with T cell receptors specific to an FMNL1 peptide to treat lymphomas and other malignancies of cells of the immune system." (PMID 34685534, 2021).
myeloid leukemia (3 papers, 2022 to 2025). A clonal proliferation of myeloid cells and their precursors in the bone marrow, peripheral blood, and spleen. "It has been determined that the expression of FMNL1 is increased in many cancer types of hematopoietic origin, such as myeloid leukemia, lymphoid leukemia, and non-Hodgkin lymphoma, but its expression in solid tumors is a subject that has just begun to be studied." (PMID 40864802, 2025). "FMNL1 is highly expressed in lymphoid and myeloid leukemias, nonlymphomas, Hodgkin's, and malignant lymphoid and myeloid cell lines, among other hematopoietic malignancies." (PMID 36124068, 2022).
non-Hodgkin lymphoma (3 papers, 2021 to 2025). Distinct from Hodgkin lymphoma both morphologically and biologically, non-Hodgkin lymphoma (NHL) is characterized by the absence of Reed-Sternberg cells, can occur at any age, and usually presents as a localized or generalized lymphadenopathy associated with fever and weight loss. "Human leukocyte formin or FMNL1 is mainly expressed in lymphoid tissues, such as the spleen and thymus, and the haematopoietic tissues; in addition, it is overexpressed in human hematological malignancies, more specifically in non-Hodgkin lymphoma and in leukemic cell lines." (PMID 34115237, 2021).
autoimmune disease (2 papers, 2020 to 2024). A disorder resulting from loss of function or tissue destruction of an organ or multiple organs, arising from humoral or cellular immune responses of the individual to their own tissue constituents. "In that study, we found that FMNL1-deficient T cells had impairments in both trafficking to inflamed tissues and induction of autoimmune disease." (PMID 39430739, 2024). "Our observations of T cell induced EAE and type 1 diabetes models suggest that reduced trafficking by FMNL1-deficient T cells to sites of inflammation plays a role in impairing the induction of autoimmune disease." (PMID 32510333, 2020). "Additionally, our previous work on FMNL1 demonstrated that FMNL1 deficient T cells have reduced capacity to induce T cell-mediated autoimmune disease." (PMID 39430739, 2024). "Furthermore, we found that FMNL1 deficiency impaired the ability of self-reactive T cells to induce autoimmune disease." (PMID 32510333, 2020). "Furthermore, FMNL1-deficiency impairs the ability of self-reactive effector T cells to induce autoimmune disease." (PMID 32510333, 2020). "Given that similar trafficking and disease induction defects were observed in two different autoimmune models, together our data support that FMNL1 broadly promotes trafficking of effector T cells to sites of inflammation enabling them to cause autoimmune disease." (PMID 32510333, 2020). "Furthermore, FMNL1 deficiency in T cells impairs their ability to induce autoimmune disease, suggesting that targeting of FMNL1 may be therapeutically beneficial." (PMID 32510333, 2020). "Our group has previously demonstrated that FMNL1 is required for activated T cell migration through micro-fabricated microchannels in vitro and trafficking to tissues in autoimmune disease models in vivo." (PMID 39430739, 2024). "We next wanted to determine whether our observation on FMNL1 regulation of T cell trafficking to the islets extended to other inflamed tissues and autoimmune disease settings." (PMID 32510333, 2020). "Our observations that FMNL1 deficiency in T cells impairs their ability to traffic to autoimmune inflammatory sites and induce autoimmune disease in both EAE and type 1 diabetes suggest that FMNL1 may be a potential therapeutic target for autoimmune disease treatment." (PMID 32510333, 2020). "Thus, our observations here present the opportunity to examine the function of FMNL1 in T cell trafficking and autoimmune disease without the potential confounding effects of altered lymphocyte development and proliferation." (PMID 32510333, 2020).
Autoimmunity (2 papers, 2020 to 2024). The occurrence of an immune reaction against the organism's own cells or tissues. "Together, our data identify FMNL1 as a novel mediator of T cell trafficking and transmigration across restrictive endothelial barriers and a regulator of self-reactive T cell autoimmunity." (PMID 32510333, 2020). "Here we report that while FMNL1 is dispensable for lymphocyte development and homeostatic naive T cell trafficking, it is important for activated T cell trafficking to inflammatory sites and for enabling T cell-mediated autoimmunity." (PMID 32510333, 2020).
IgA glomerulonephritis (2 papers, 2022). Inflammation of a specific segment of glomeruli within the kidney. "More recently, autoantibodies against Formin-like 1 (FMNL1) were detected in patients with PMN as well as other forms of glomerular disease (IgA nephropathy and focal segmental glomerulosclerosis), which recognize FMNL1 expression on macrophages." (PMID 36405681, 2022).
lung carcinoma (2 papers, 2019 to 2020). "FMNL1 was reported to regulate GOLGA2 distribution and expression during spindle formation in mouse oocytes, whereas GOLGA2 downregulation suppressed gastric and lung cancers invasion." (PMID 31861134, 2019).
membranous nephropathy (2 papers, 2022 to 2024). "An example of the application of the peptide array is the discovery in membranous nephropathy of many new circulating autoantibodies including formin-like-1, a protein of podosomes that is implicated in macrophage movements." (PMID 39684370, 2024).
T cell lymphomas (2 papers, 2021 to 2024). "Early investigations of FMNL1 revealed that FMNL1 is overexpressed in T cell lymphomas and ectopic expression in other cancers is associated with aggressive infiltration and poor patient prognosis." (PMID 39430739, 2024).
acute kidney failure (1 paper, 2025). "Furthermore, the Kidney Tissue Atlas developed by the Kidney Precision Medicine Project (KPMP) revealed that FMNL1 exhibits elevated RNA expression in acute kidney failure and CKD patients compared to healthy individuals." (PMID 39994404, 2025).
autoimmune uveitis (1 paper, 2021). An autoimmune form of uveitis (disease). "Furthermore, the higher concentration of formin like 1 in CD4+ T cells of ERU cases was also linked to the activation of those cells in the quiescent stage of equine recurrent autoimmune uveitis." (PMID 34385998, 2021).
diabetes (1 paper, 2020). "(E) FMNL1 deficiency in self-reactive T cells delays and partially protects from diabetes." (PMID 32510333, 2020). "Since type 1 diabetes is driven by destruction of beta cells by islet-infiltrating antigen specific T cells, we next investigated whether the observed trafficking defects in FMNL1-deficient T cells would affect their ability to induce diabetes." (PMID 32510333, 2020). "While 100% of mice receiving control T cells developed diabetes, only 44% of mice receiving FMNL1 KO T cells developed diabetes." (PMID 32510333, 2020). "Diabetes incidence of mice receiving control or FMNL1 KO OT-I and OT-II T cells." (PMID 32510333, 2020).
glomerulonephritis (1 paper, 2022). A renal disorder characterized by damage in the glomeruli. "We also observed that anti-FMNL1 IgGs were not restricted uniquely to MN and high circulating levels were detected in patients with other glomerulonephritis such as idiopathic and genetic FSGS and IgAGN." (PMID 35953506, 2022).
hepatocellular carcinoma (1 paper, 2023). A malignant tumor that arises from hepatocytes. "In this research, the bulk RNA-seq data from the Cancer Genome Atlas (TCGA) database was utilized to explore the correlation between FMNL1 and features of TME, and FMNL1 was found to be tightly correlated with features of TME in not only hepatocellular carcinoma (HCC) but also multiple cancer types." (PMID 37859818, 2023).
liver fibrosis (1 paper, 2023). "In the human liver, the expression levels of Fmnl1 and Myh9 in the MMD system (CCR2/CD68/CD11c+ cells in humans) were also increased with collagen deposition, and the expression levels of Fmnl1 and Myh9 increased with aggravation of the liver fibrosis stage (all p<0.05)." (PMID 36911682, 2023).